ZBP1 (Z-DNA binding protein 1)
Diseases named in the same sentence as ZBP1 in open-access papers (continued):
Sharing a sentence is not in itself a finding about the gene and the disease.
cancer (continued). "Of these DEGs, 6 (EGFR, GATA3, DIABLO, CFLAR, RIPK3, and MAPK8) were repressed, while (ZBP1, PLK1, SPATA2, BCL2, ALK, FASLG, TNFRSF21, and LEF1) were upregulated in cancer cases." (PMID 35610275, 2022). "To promote the clinical transformation of the NRGs signature, we further identified the sensitive FDA-approved drugs for multiple cancer cell types with higher expressions of FASLG, TLR3, and ZBP1." (PMID 35165523, 2022). "Clinical studies have found their expression to be reactivated in a range of tumors, hinting at a potential role for ZBP1 and IMP3 in cancer pathogenesis." (PMID 31570709, 2019). "The observed invasiveness was not seen in the cells that expressed the KIF5A tail (806–1032), suggesting the importance of endogenous communication of ZBP1 and KIF11 in the invasiveness of cancer cells." (PMID 25588836, 2015). "Moreover, a unique binding partner to ZBP1, adenosine deaminase acting on RNA 1 (ADAR1), is involved in RNA editing, stress mechanisms, and diseases, including cancers." (PMID 38169587, 2024). "By leveraging the immunogenic properties of nuclear necroptosis and the interaction between ZBP1 and the cGAS-STING pathway, it may be possible to develop novel strategies for cancer treatment that enhance immune responses against tumors." (PMID 38523155, 2024). "Consistent with this study, we found ZBP1 expression is absent in all checked human cancer cell lines." (PMID 39465258, 2024). "Based on these observations, it is plausible that cancer-specific disruptions in MRN, cGAS, STING and/or ZBP1 may influence responses to DNA damaging therapy and immunotherapy, warranting further exploration of their clinical implications." (PMID 38200309, 2024). "In addition, the important functions of ZBP1 have also been confirmed in human diseases, including SARS-CoV-2 infection, cancer, and skin inflammation." (PMID 36615244, 2022). "Moreover, IMP1/ZBP1 and IMP3 have almost identical developmental expression patterns, and both are reported to be potential oncogenic proteins involved in a range of cancers." (PMID 34685634, 2021). "As the unique two proteins containing Zα domains in mammals, it is not surprising that ADAR1 and ZBP1 may be involved together in the regulation of cancer." (PMID 37771585, 2023). "ADAR1’s restriction on ZBP1 signaling complements the mechanism of the oncogenic role of ADAR1, and developing new drugs capable of repressing ADAR1 function or directly activating ZBP1 may be the new strategy for treating cancer." (PMID 36142136, 2022). "These rescue experiments reaffirm that ADAR1i-124-mediated cancer cell death and IFN/ISG induction are dependent solely on the MDA5 and ZBP1 pathways, ruling out any non-specific or off-target effects." (PMID 41608661, 2026).
infectious disease (11 papers, 2021 to 2025). A disorder directly resulting from the presence and activity of a microbial, viral, or parasitic agent in humans. "Triggered by Z-DNA binding protein 1 (ZBP1) and mediated by the PANoptosome complex, PANoptosis is activated in various infectious diseases, such as influenza A virus infection." (PMID 37547288, 2023). "It has been reported that there are three kinds of programmed cell death including apoptosis, pyroptosis and necroptosis in infectious diseases, they have a common upstream regulatory target ZBP1, which is named ZBP1 dependent PANoptosis." (PMID 35655858, 2022). "Previous studies showed that ZBP1-derived PANoptosis was induced in infectious diseases." (PMID 39465258, 2024). "In particular, ZBP1 signaling could be a target for therapeutic exploitation in infectious diseases in the near future." (PMID 36040212, 2022). "ZBP1 may contribute to pyroptosis, apoptosis and necroptosis in infectious diseases." (PMID 36539813, 2022). "Thus, the relevance of ZBP1 to host vulnerability in infectious diseases could be remedied by this new CRISPR-Cas9 ZBP1−/− mouse." (PMID 33526566, 2021). "24, and TETHERIN) and Z-DNA binding protein 1 (ZBP1, also known as DAI, DLM1, DLM-1, and C20orf183), could be identified in canonical pathways related to immunity and infectious diseases." (PMID 39874350, 2025).
inflammation (3 papers, 2022 to 2024). Aberrant reaction of the microcirculation characterized by movement of fluid and leukocytes from the blood into extravascular tissues. "However, our previous work in mice lacking FADD in intestinal epithelial cells (IECs) showed that TNFR1 cooperates with ZBP1 to induce necroptosis-mediated gut inflammation, revealing an intricate interplay between TNFR1 and ZBP1 in causing IEC necroptosis." (PMID 38849574, 2024).
neurodegenerative disease (3 papers, 2024 to 2026). A disorder of the central nervous system characterized by gradual and progressive loss of neural tissue and neurologic function. "This work further suggests that targeting ZBP1 may offer a therapeutic strategy to treat tau-mediated neurodegenerative disease." (PMID 41972681, 2026). "Therefore, future therapeutic strategies targeting Zbp1 in neurodegenerative diseases should carefully consider these potential differences." (PMID 39853924, 2025).
adenocarcinoma (2 papers, 2010 to 2024). A common cancer characterized by the presence of malignant glandular cells. "A marked difference in ZBP1 mRNA expression betweenlung adenocarcinoma tissue and its neighboring normal tissue was noted (P < 0.001)." (PMID 38369516, 2024).
bacterial infection (2 papers, 2022 to 2024). "In contrast to the well-established role of ZBP1 as a viral sensor, its function during bacterial infection is less understood." (PMID 39850894, 2024). "Therefore, we assessed the involvement of ZBP1 in macrophage cell death mediated by bacterial infection through LDH release in a time-lapse experiment." (PMID 39850894, 2024). "The most common role of ZBP1 is its involvement in antiviral responses, but in addition to regulating virus invasion, ZBP1 may also be required for bacterial infection, such as Yersinia pestis and Francisella infection." (PMID 36539813, 2022). "However, ZBP1 does not influence the production of proinflammatory mediators, inflammasome activation and it is dispensable to control bacterial infection in mice or replication in macrophages." (PMID 39850894, 2024).
brain diseases (1 paper, 2024). "Interestingly, the cellular processes we find to be affected by altered miR-99b-5p and Zbp1 levels have also been implicated in other brain diseases." (PMID 38528182, 2024).
peripheral neuropathy (1 paper, 2021). A disorder affecting the peripheral nervous system. "Understanding how the level of ZBP1 is regulated, and why its regulation fails following injury in the diabetic state, may provide new strategies to enhance axonal regeneration and overcome deficits that lead to peripheral neuropathy." (PMID 34949989, 2021).
ZBP1 also shares sentences with these, for which no sentence is quoted: head and neck squamous cell carcinoma (2 papers); pneumonia (2); viral diseases (2); acute liver failure (1); acute myeloid leukemia (1); adrenocortical carcinoma (1); biliary atresia (1); cardiovascular diseases (1); colorectal tumor (1); Crohn disease (1); cryptococcosis (1); cyst (1); dengue (1); dermatitis (1); Erythema (1); esophageal cancer (1); fibrosarcoma (1); gastric cancer (1); Heat Stroke (1); invasive carcinoma (1); mesothelioma (1); neurological diseases (1); pancreatic adenocarcinoma (1); pancreatic cancer (1); Parkinson disease (1); sarcoma (1); Seizure (1); spinal cord injury (1); sporotrichosis (1); tuberculosis (1).
A further 2 diseases each share a sentence with ZBP1 in 1 paper.